TMCO2 (transmembrane and coiled-coil domains 2)
Synonyms: dJ39G22.2
Tractability: Antibody: UniProt predicts a signal peptide or a membrane-spanning region.
Gene: Protein-coding gene on chromosome 1 (40,245,947 to 40,251,684, forward strand). Ensembl gene ENSG00000188800.
Subcellular location: Membrane
Gene Ontology:
Molecular function: protein binding
Cellular component: nucleus; inner acrosomal membrane; membrane
Genetic constraint (gnomAD): Loss-of-function variants: 9 observed, 15.09 expected, observed/expected ratio (o/e) 0.6, 90% interval 0.36 to 1.04. The upper end of that interval is the gene's LOEUF score, 1.04, which puts it in group 4 of 6, group 1 being the genes least tolerant of losing a copy. Missense variants: 172 observed, 201.79 expected, observed/expected ratio (o/e) 0.85, 90% interval 0.75 to 0.97. Synonymous variants: 77 observed, 77.87 expected, observed/expected ratio (o/e) 0.99, 90% interval 0.82 to 1.2.
Homologues: Orthologues: chimpanzee TMCO2 (98% identical), macaque TMCO2 (90% identical), mouse Tmco2 (75% identical), rat Tmco2 (75% identical), dog TMCO2 (74% identical), rabbit TMCO2 (74% identical), pig TMCO2 (72% identical), guinea pig TMCO2 (71% identical).